CDKN2A (cyclin dependent kinase inhibitor 2A)
Diseases named in the same sentence as CDKN2A in open-access papers (continued):
Sharing a sentence is not in itself a finding about the gene and the disease.
carcinoma in situ (9 papers, 2011 to 2023). "Within our retrospective LCM cohort, 70% of patients showed significantly increased expression of CDKN2A (a proxy marker for HPV infection) in regions of carcinoma in situ relative to normal epithelium." (PMID 26334652, 2015). "After the application of inclusion criteria, we excluded 3 patients with visceral melanoma and 54 others that did not exhibit either personal or familial characteristics superposable to CDKN2A positivity; no case of melanoma in situ was detected in the analyzed individuals." (PMID 38138255, 2023).
colorectal tumors (9 papers, 2012 to 2025). "We observed that CDKN2A was positively stained in the nuclear of colorectal tumor cells compared with the normal tissue." (PMID 36132144, 2022). "Moreover, the frequencies of APC or CDKN2A gene abnormalities in SIT are significantly lower than those in colorectal tumors." (PMID 35566730, 2022). "For example, the frequencies of APC and CDKN2A gene abnormalities in small intestinal adenocarcinoma are lower than in colorectal cancer, but KRAS gene abnormalities are observed as frequently as in colorectal tumors." (PMID 35566730, 2022). "Finally, we performed methylation-specific PCR on 76 colorectal tumors to determine DNA methylation status for CSMD1 and known methylation targets ALX4, RUNX3, NEUROG1, and CDKN2A." (PMID 23505554, 2013). "Here, we evaluated the prevalence of hypermethylation in the CDH1, CDKN2A, DAPK, and TIMP2 suppressor tumors genes of colorectal tumors tissue and their non-neoplastic adjacent margin using methylation specific PCR (MSP), which is a highly sensitive and specific technique." (PMID 26363785, 2015).
ischemic stroke (9 papers, 2009 to 2024). A stroke disorder caused by obstruction of blood flow to the brain, due to thrombotic (local blood clot formation) or embolic (due to a blood clot or other material traveling from another site) event. "DNA methylation levels of CDKN2A/2B were measured in 322 ischemic stroke patients using peripheral blood leukocytes." (PMID 27905995, 2016). "In this study, we tested this hypothesis by evaluating the degree of DNA methylation in CDKN2A/2B and the carotid calcification load in a cohort of patients with ischemic stroke." (PMID 27905995, 2016). "Considering that CDKN2A/2B is a frequently reported site for DNA methylation, this study aimed to evaluate whether carotid artery calcification (CarAC) is related to methylation levels of CDKN2A/2B in patients with ischemic stroke." (PMID 27905995, 2016).
laryngeal carcinoma (9 papers, 2004 to 2024). Carcinoma that arises from the laryngeal epithelium.
malignant peripheral nerve sheath tumor (9 papers, 2013 to 2024). Malignant peripheral nerve sheath tumor (MPNST) is a rare and often aggressive soft tissue sarcoma occurring in a wide range of anatomical sites. "Analysis of 7733 STS patients from Foundation One showed high prevalence of CDKN2A alterations in malignant peripheral nerve sheath tumors, myxofibrosarcomas, and undifferentiated pleomorphic sarcomas." (PMID 31528332, 2019).
renal carcinoma (9 papers, 2009 to 2025). A carcinoma arising from the epithelium of the renal parenchyma or the renal pelvis. "To support the significance of CDKN2A loss in renal cancer, we further analyzed the available TCGA data and found worst survival for ccRCC and pRCC patients with CDKN2A alteration, as compared to wild type." (PMID 27144525, 2016). "CDKN2A promotes the migration of renal cancer cells, while MYCN inhibits their migration." (PMID 37878133, 2023). "Additionally, a study in renal carcinoma demonstrated that genistein suppresses tumor cell proliferation by enhancing CDKN2A expression through promoter hypomethylation, suggesting an epigenetic mechanism that may underlie CDKN2A activation in certain cancers." (PMID 41226409, 2025). "CDKN2A can accelerate the invasion and migration of renal cancer cells and MYCN inhibits the invasion and migration of renal cancer cells through wound healing assay and transwell invasion assays." (PMID 37878133, 2023). "Renal cancer of all types can potentially be diagnosed by detecting promoter hypermethylation with a panel of genes including VHL, p16/CDKN2a, p14ARF, APC, RASSF1A, and Timp-3." (PMID 24065096, 2013).
vulvar carcinoma (9 papers, 2013 to 2021). "Although the numbers of vulvar carcinomas included are small, vulvar cancer seems to have a different mutational spectrum as compared to other gynaecological malignancies with CDKN2A (12%) and HRAS (8%) most often affected." (PMID 24671188, 2014). "However, since CDKN2A mutations in squamous cell carcinoma of the skin are reported to be more often point mutations than (large) deletions, we believe that adding CDKN2A point mutations to the panel can give valuable information, especially for vulvar cancer." (PMID 24671188, 2014). "In the present study, 25 vulvar carcinomas (of which 19 HPV-negative tumours) were analysed, and one PIK3CA, 3 CDKN2A, and 2 HRAS mutations were detected in the HPV-negative carcinomas." (PMID 24671188, 2014). "The results of our study prompt further investigation of the roles of HRAS and CDKN2A in vulvar cancer." (PMID 24671188, 2014). "CDKN2A is not truly a hotspot mutated gene too, but it was added to the panel because of its high predicted relevance in vulvar cancer, and because we expected to obtain a fair coverage of the gene." (PMID 24671188, 2014).
acral melanomas (8 papers, 2020 to 2025). "Regarding the cell cycle pathway, CDK4/CCND1 amplifications were more common in NAM and CDKN2A/B loss occurred mostly in acral melanoma." (PMID 36983205, 2023). "CDKN2A mutations are less common in acral melanoma, with only 9–18% of acral melanomas showing somatic CDKN2A alterations, and these alterations were predominantly homozygous deletions." (PMID 33076392, 2020). "Additionally, CCND1 amplification and CDKN2A loss—which are common genetic alterations seen in acral melanoma—can activate the CDK4 pathway, promoting primary resistance to therapy." (PMID 41010951, 2025). "In addition, genetic alterations in CDK4 pathway components (CDK4, CCND1, and CDKN2A), which are particularly common in Asians, have been associated with innate resistance to PD-1 blockade in patients with acral melanoma." (PMID 34149718, 2021). "Aberrations in MAPK, PI3K/AKT/PTEN, TERT, WNT, and CDK4/CDKN2A signaling pathways are frequent in acral melanoma." (PMID 34149718, 2021). "Deletions of gene CDKN2A appear to lead to resistance to immunotherapy and, in combination with the deregulation of CDK4, worsen prognosis in acral melanoma." (PMID 32825510, 2020). "Additionally, acral melanomas frequently harbor copy number gains in CCND1 and CDK4 and losses of CDKN2A, and a large preclinical study showed that palbociclib monotherapy was effective in treating acral melanoma patient derived xenograft tumors with various alterations to Cyclin–CDK circuitry." (PMID 40282469, 2025).
anaplastic meningioma (8 papers, 2014 to 2025). A WHO grade III meningioma characterized by the presence of malignant morphologic features, including malignant cytology and a very high mitotic index (20 or more mitoses per ten high power fields). "Our results suggest that MTAP IHC can be unreliable as a sole surrogate for CDKN2A loss in anaplastic meningioma." (PMID 40227557, 2025). "This threshold was chosen based on the magnitude of the AUC peak corresponding to loss of the CDKN2A/B locus on chromosome 9p, a molecular feature that is sufficient for diagnosis of anaplastic meningioma, WHO grade 310." (PMID 40603285, 2025). "TERT promoter mutations and homozygous deletions of CDKN2A/B have been identified as indicators of worse prognosis and were incorporated into the 2021 WHO classification criteria for the diagnosis of anaplastic meningioma." (PMID 40227557, 2025). "Loss of function in chromosome 9 due to the deletions of the cyclin-dependent kinase inhibitors 2A (CDKN2A) and 2B (CDKN2B) has been associated with the progression from Grade 2 to anaplastic meningioma (Grade 3)." (PMID 38137885, 2023). "Loses of the CDKN2A (p16), p14 (ARF), and CDKN2B (p15) are the main alterations that have been linked to chromosome 9 and are primarily found in anaplastic meningiomas." (PMID 25485306, 2014). "Additionally patient #2 suffered from anaplastic meningioma CNS WHO grade 3 with BAP1 mutation, FANCC mutation and homozygous CDKN2A/B deletion in both manifestations." (PMID 36641486, 2023). "In addition, homozygous focal deletions of the cyclin-dependent kinase inhibitor 2A (CDKN2A) gene, located at 9p21, have been observed at high frequency in anaplastic meningiomas." (PMID 32642869, 2020). "CDKN2A deletions are key markers of malignancy and were integrated into the 2021 WHO classification for anaplastic meningiomas." (PMID 40227557, 2025). "Loss of chromosome 9p21.3, which harbors the critical tumor suppressor CDKN2A, was observed in IOMM-Lee, a cell line derived from an anaplastic meningioma." (PMID 28552950, 2017). "The integrated diagnoses of the initial lesions (under consideration of the TERT promoter and CDKN2A/B deletion) were three CNS WHO grade 1 tumors (microcystic, meningothelial and papillary), one CNS WHO grade 2 tumor (atypical) and one anaplastic meningioma, CNS WHO grade 3." (PMID 36641486, 2023). "Finally, the second molecular alteration sufficient for diagnosis of anaplastic meningioma, CDKN2A/B co-deletion, has not been analyzed." (PMID 37686690, 2023).
astrocytic tumor (8 papers, 2012 to 2025). A glial tumor of the brain or spinal cord showing astrocytic differentiation. "Astrocytic tumors with CDKN2A/B homozygous deletions (HD), EGFR mutation and/or amplification (mut/amp), or PTEN mut/loss had a significantly higher T/N ratio on the MET-PET images compared with those without these alterations." (PMID 40786409, 2025). "It should be noted that recently homozygous CDKN2A deletions were identified as prognostic markers for malignant astrocytic tumors with IDH mutation." (PMID 31623667, 2019). "The presence of germline CDKN2A/B inactivation together with the presence of multiple anatomically, histologically, and genetically distinct astrocytic neoplasms, both with accompanying somatic loss of the remaining CDKN2A/B alleles, is diagnostic of familial melanoma-astrocytoma syndrome." (PMID 28699883, 2017). "It highlights the need for a better definition of cut offs for the determination of CDKN2A deletion status by FISH as proposed by some authors in IDH mutant astrocytic tumors." (PMID 40315229, 2025). "The findings of our retrospective small cohort study suggest that in astrocytic tumors, PTEN mut/loss, EGFR mut/amp, and CDKN2A/B HD are strong MET accumulation factors, and NF1 mut/loss is a strong FDG accumulation factor." (PMID 40786409, 2025). "Homozygous deletion has been described as the major inactivating mechanism for the CDKN2A products, while several authors have found promoter methylation of p14ARF and/or p16INK4A in a subset of astrocytic tumors." (PMID 22389839, 2012). "The MET-PET T/N ratio was significantly higher in patients with astrocytic tumors with CDKN2A/B HD as compared to those without HD." (PMID 40786409, 2025). "Therefore, the present study aimed to evaluate the expression and methylation profiles of the genes CDKN2A, CDKN2B, CDC6, Bmi-1, CCND1, and RB1 in astrocytic tumors in the northern region of Brazil." (PMID 26317630, 2015).
basal cell carcinoma (8 papers, 2004 to 2023). A carcinoma involving the basal cells. "Since the CDKN2a/ p16INK4a, p19ARF and p15INK4b tumor suppressor genes do not appear to be responsible for the observed abnormalities, other genes at 9p21-p22 may be involved in the pathogenesis and progression pathway of basal cell carcinomas." (PMID 15160522, 2004). "Since the CDKN2a/p16INK4a, p19ARF and p15INK4b tumor suppressor genes do not appear to be responsible for the abnormalities observed, other genes at 9p21-p22 may be involved in the pathogenesis and progression pathway of basal cell carcinomas." (PMID 15160522, 2004).
brain cancer (8 papers, 2010 to 2023). A primary or metastatic malignant neoplasm affecting the brain. "One example is a CDKN2A deletion that sensitizes brain cancer cells to palbociclib (a CDK4/6 inhibitor) and to knockouts in CDK4 and CDK6 genes." (PMID 35614096, 2022).
ganglioglioma (8 papers, 2018 to 2024). A well differentiated, slow growing neuroepithelial neoplasm composed of neoplastic, mature ganglion cells and neoplastic glial cells. "CDKN2A (and adjacent CDKN2B) loss has been previously identified in a small minority of gangliogliomas as well as in other pediatric CNS tumors, such as pleomorphic xanthroastrocytoma (where CDKN2A/B loss is typical)." (PMID 36966348, 2023). "Three gangliogliomas with BRAF p.V600E mutation had concurrent CDKN2A homozygous deletion (SF-GG-3, SF-GG-9, and SF-GG-11) and one of these three tumors additionally harbored a subclonal missense mutation in the PTEN tumor suppressor gene (SF-GG-3)." (PMID 29880043, 2018). "The prognostic significance of CDKN2A/B loss in ganglioglioma is unclear though there may be some association with more adverse histopathological features and poorer prognosis." (PMID 36966348, 2023). "However, our study shows that a small subset of pathologically-confirmed gangliogliomas can harbor this identical combination of CDKN2A homozygous deletion and BRAF p.V600E mutation, indicating that this genetic pattern is not entirely specific to pleomorphic xanthoastrocytomas." (PMID 29880043, 2018). "Crucially, PXA’s molecular signature, characterized by MAPK pathway activation predominantly via BRAF V600E and the CDKN2A/B deletion, provides a robust tool to differentiate it from close differentials such as ganglioglioma." (PMID 37998600, 2023). "Acquisition of a hemizygous CDKN2A deletion was identified in the patient with a desmoplastic infantile ganglioglioma following systemic therapy (Patient #41)." (PMID 33153497, 2020). "No focal amplifications or homozygous deletions were identified other than the three gangliogliomas with focal CDKN2A homozygous deletion." (PMID 29880043, 2018). "Moreover, PXA and ganglioglioma share the BRAF V600E driver variant and occasional gangliogliomas have been reported carrying CDKN2A/B homozygous deletions." (PMID 39294363, 2024). "Together, this study highlights that ganglioglioma is characterized by genetic alterations that activate the MAP kinase pathway, with only a small subset of cases that harbor additional pathogenic alterations such as CDKN2A deletion." (PMID 29880043, 2018). "None of the gangliogliomas in this cohort showed genetic alterations in components of this pathway, except for one ganglioglioma that recurred after gross total resection and harbored a subclonal PTEN missense mutation (in addition to BRAF p.V600E mutation and CDKN2A homozygous deletion)." (PMID 29880043, 2018). "The revised PD of ganglioglioma in these scenarios was grounded by the presence of dysmorphic ganglion cells and the absence of a combined BRAF and CDKN2A/B molecular signature." (PMID 37998600, 2023).
hereditary cancer syndromes (8 papers, 2017 to 2025). "This study contributes valuable insights into the genetic underpinnings of hereditary cancer syndromes, urging the continued exploration of personalized treatment approaches for individuals with CDKN2A mutations." (PMID 38137564, 2023). "Germline mutations within CDKN2A have affiliations with hereditary cancer syndromes." (PMID 37936609, 2023). "As a result, the use of PGT may be less urgent for CDKN2A PV carriers compared to individuals with hereditary cancer syndromes that involve burdensome preventive measures and surveillance methods and." (PMID 38822936, 2024).
histiocytic sarcoma (8 papers, 2009 to 2024). An aggressive malignant neoplasm with a poor response to therapy, usually presenting as stage III/IV disease. "Likewise, tyrosine kinase inhibitor resistance of Philadelphia chromosome-positive leukemia correlates with deletion of the CDKN2 gene, and cooperativity between PTEN loss and loss of Cdkn2a and Arf in histiocytic sarcoma has been reported." (PMID 37063827, 2023). "Germline variants in the CDKN2A/B loci have also been previously associated with risk of developing OSA in high-risk dog breeds and also of developing histiocytic sarcoma in Bernese Mountain dogs." (PMID 33556121, 2021). "Exon 2 of CDKN2A was also sequenced from DNA obtained from blood samples from three Bernese mountain dogs, four flat-coated retrievers with histiocytic sarcoma, and five flat-coated retrievers free from tumours, two golden retrievers and four Labrador retrievers." (PMID 19643034, 2009). "Focal deletions involving the MTAP and CDKN2A/B loci on CFA 11q16 are among the most highly recurrent somatic CNAs in a broad range of naturally occurring canine cancers, including appendicular osteosarcoma, histiocytic sarcoma, and non-Hodgkin’s lymphoma." (PMID 25957863, 2015).
intrahepatic cholangiocarcinoma (8 papers, 2021 to 2024). A carcinoma that arises from the intrahepatic bile duct epithelium in any site of the intrahepatic biliary tree. "For patients with intrahepatic cholangiocarcinoma (ICC), CDKN2A/B loss was associated with shorter overall survival." (PMID 36119486, 2022). "BRCA2, CDKN2A, and FGFR2 mutations were most frequently identified in case of intrahepatic cholangiocarcinoma." (PMID 34316332, 2021). "In biliary tract cancers (BTCs), which encompass gallbladder cancer, intrahepatic cholangiocarcinoma (ICC), and extrahepatic cholangiocarcinoma (EHC), alterations in the CDKN2A gene are frequently observed." (PMID 38137564, 2023).